KPNA2 (karyopherin subunit alpha 2)
Diseases named in the same sentence as KPNA2 in open-access papers (continued):
Sharing a sentence is not in itself a finding about the gene and the disease.
glioblastoma (8 papers, 2018 to 2023). The most malignant astrocytic tumor (WHO grade IV). "KPNA2 has been shown to cause metabolic reprograming in glioblastoma through the induction of cMYC." (PMID 33114077, 2020). "For example, deficiency of KPNA2 promoted cell apoptosis in glioblastoma multiforme." (PMID 30560474, 2019). "Considering the broad involvement of KPNA2 in the metabolic reprogramming and tumor growth of glioblastomas, we hypothesized that the role of KPNA2 in glioblastomas may be linked with c-myc." (PMID 30115078, 2018). "We have previously shown that the nucleocytoplasmic carrier karyopherin a2 (KPNA2) is overexpressed in glioblastoma multiforme (GBM) whereas its expression is inversely associated with patient prognosis." (PMID 30323892, 2018). "Furthermore, down-regulation of KPNA2 in the glioblastoma cells caused a remarkable decrease of cell viability and rise in the survival rates of xenograft mice, evidently supporting the association between high level of KPNA2 and a worse clinical outcome." (PMID 30115078, 2018). "The expressions of KPNA2 in glioblastoma and normal human brain samples were analyzed by immunohistochemical analysis." (PMID 30115078, 2018). "Knockdown of KPNA2 in the glioblastoma cell lines U87 and U251 decreased deoxyglucose uptake, activities of the key glycolytic enzymes and lactate production." (PMID 30115078, 2018). "miR-1297 inhibits KPNA2 in glioblastoma to negatively regulate metabolic reprogramming." (PMID 36968605, 2023). "In a word, KPNA2 might play an important role in the metabolic transformation of glioblastoma cells, which exerts vital effects on tumor initiation and progression." (PMID 30115078, 2018). "Moreover, KPNA2 regulates cellular metabolism through c-myc signaling in glioblastoma." (PMID 34903711, 2021). "A comparable result was observed in the U251 glioblastoma cells (data not shown), further suggesting that KPNA2 played an important role in mediating the transportation of c-myc into the nucleus." (PMID 30115078, 2018).
cervical carcinoma (7 papers, 2013 to 2025). A carcinoma arising from either the exocervical squamous epithelium or the endocervical glandular epithelium. "We also counted the KPNA1-and KPNA2-positive cells in normal and cervical cancer tissues and calculated the pathological scores associated with KPNA1/2 expression." (PMID 35991835, 2022). "In support of regulatory RNA networks in cervical cancer, previous findings have shown that hsa_circ_0000021 and KPNA2 are overexpressed and act as oncogenic drivers by negatively regulating miR-3940-3p." (PMID 41465546, 2025). "Mechanistically, hsa_circ_0000021 promotes cervical cancer progression by sponging miR-3940-3p, which targets KPNA2." (PMID 41465546, 2025). "Functional studies demonstrated that silencing either hsa_circ_0000021 or KPNA2 suppressed cervical cancer cell proliferation, invasion, and tumor growth, whereas inhibition of miR-3940-3p enhanced malignancy." (PMID 41465546, 2025). "By contrast, an elevated expression of KPNA2 in cervical cancer tissues was observed, in line with the literature describing the overexpression of KPNA2 as a biomarker for multiple types of cancer, including cervical cancer." (PMID 35991835, 2022). "Higher expression of KPNA2 was found in cervical cancer tissues compared with that in normal samples." (PMID 35991835, 2022). "As a member of the karyopherin family for nuclear protein transport, KPNA2 has been observed to show abnormally high expression in cervical cancer patients." (PMID 35991835, 2022). "The objective of this study was to investigate the expression of KPNA1 and KPNA2 in cervical cancer tissue with different histologic grades and cell lines, as well as the effects of the KPNA1 expression level on Hela cell proliferation." (PMID 35991835, 2022). "The staining results showed that the immunoreactivity for KPNA1 was significantly lower in the cervical cancer tissues than the normal tissues, whereas KPNA2 displayed the opposite trend, with increasing immunostaining in the cervical cancer tissue over the normal tissue." (PMID 35991835, 2022). "We then detected the expression of KPNA1 and KPNA2 in human cervical carcinoma Hela and C33A cells." (PMID 35991835, 2022). "A number of studies have reported that KPNA2, a member of the karyopherin α family, is overexpressed in multiple forms of cancer, including breast cancer, lung cancer, esophageal squamous cell carcinoma, colon cancer, prostate cancer and cervical cancer." (PMID 35991835, 2022). "For example, CRM1, KPNB1 and KPNA2 are overexpressed in cervical cancer cells." (PMID 31288861, 2019). "Recent studies have revealed that KPNs including KPNA2 are overexpressed in various kinds of tumors such as breast cancer, cervical cancer, non-small cell lung cancer, prostate cancer, and primary cutaneous melanoma, and that expression levels in these tumors are closely associated with prognosis." (PMID 24098495, 2013). "Interestingly, siRNA-medicated KPNA2 knockdown studies revealed a different cellular response to KPNA2 inhibition in prostate and cervical cancer cell lines." (PMID 24098495, 2013). "Therefore, inhibition of KPNA2-mediated excessive nuclear transport of oncoproteins by specific inhibitor may be a new treatment strategy for patients with cervical cancer." (PMID 35991835, 2022). "We collected the medical data of 106 patients with cervical cancer and investigated the protein expression of KPNA1 and KPNA2 by immunohistochemistry and western blot." (PMID 35991835, 2022). "To further confirm the correlation between KPNA1/2 levels and the degree of malignancy of cervical cancer, we further detected the expression of KPNA1 and KPNA2 in cervical tumor tissues with different histopathologic grades by immunohistochemical staining." (PMID 35991835, 2022).
cervical carcinoma (continued). "Interestingly, this event was also observed in MDA-MB-231 cells, suggesting that E2F/Dp1 heterodimers bind and activate the Kpna2 promoter in several types of cancer cells, including NSCLC, breast and cervical cancer cells." (PMID 27009856, 2016). "In prostate cell line PC3, proliferation and viability were significantly reduced when KPNA2 expression was inhibited, whereas there was no significant change in a cervical cancer cell line." (PMID 24098495, 2013).
lung adenocarcinoma (6 papers, 2016 to 2025). A carcinoma that arises from the lung and is characterized by the presence of malignant glandular epithelial cells. "To elucidate the regulatory mechanisms of KPNA2 in lung adenocarcinoma, we further analyzed the top 200 genes associated with KPNA2 expression in lung adenocarcinoma obtained from the TCGA database, among which, we identified seven transcription factors." (PMID 41413918, 2025). "Further, high expression levels of UBE2T, TK1, and KPNA2 were associated with poor survival rates of patients with lung adenocarcinoma in TCGA data." (PMID 35884546, 2022). "Among the different genetic drivers of lung adenocarcinoma, the nuclear transport protein karyopherin subunit alpha 2 (KPNA2) has emerged as a potential oncogene." (PMID 41413918, 2025). "Our research has revealed that KPNA2 is significantly overexpressed in lung adenocarcinoma tissues, and that patients with elevated levels of KPNA2 expression typically have poorer survival outcomes, which is consistent with the findings of previous studies." (PMID 41413918, 2025). "We found that KPNA2 is upregulated in lung adenocarcinoma and that inhibiting its expression effectively reduced the proliferation of lung adenocarcinoma cancer cells." (PMID 41413918, 2025). "To this end, in this study, using siRNA silencing, we initially knocked down KPNA2 in lung adenocarcinoma cell lines, and performed CCK8 and 5-ethynyl-2ʹ-deoxyuridine assays to examine the proliferation of lung adenocarcinoma." (PMID 41413918, 2025). "Proteomic analysis on lung adenocarcinoma cells overexpressing KPNA2 revealed that an enhanced interaction between vimentin and KPNA2 leads to the recruitment of phosphorylated ERK in the cytoplasm." (PMID 37792911, 2023). "In order to confirm KPNA2 expression in CAFs, immunohistochemistry was performed on the lung adenocarcinoma tumor sample." (PMID 35884546, 2022). "In this study, we examined the function and regulatory mechanisms of KPNA2 in lung adenocarcinoma." (PMID 41413918, 2025). "In lung adenocarcinoma, patients with elevated KPNA2 expression level had worse prognosis." (PMID 34049287, 2021). "MiRNA hsa-mir-30a and lncRNA AC104472.1 constituted regulatory module for lung adenocarcinoma a with TPI1, KPNA2, MET, HSP90B1, P4HB, DSP, CDH1, and ENO1." (PMID 36138770, 2022). "To investigate the effects of KPNA2 on lung adenocarcinoma, we downloaded data relating to lung adenocarcinoma from TCGA via UCSC Xena web and compared the expression of KPNA2 in normal and tumor tissues, on the basis of which, we established that KPNA2 is highly expressed in tumor tissues." (PMID 41413918, 2025). "Moreover, our findings are consistent the operation of a positive feedback loop between the expression of KPNA2 and FOXM1, which contributes to enhancing the proliferation of lung adenocarcinoma cells." (PMID 41413918, 2025).
lymph node metastasis (6 papers, 2015 to 2024). "KPNA2 was shown to be highly expressed in GC cells and tissues and associated with lymph node metastases." (PMID 39060340, 2024). "High KPNA2 expression in IHCC was associated with lymph node metastasis (P = 0.034)." (PMID 28178675, 2017). "Furthermore, KPNA2 expression was associated with lymph node metastasis in our GC cohort." (PMID 39060340, 2024). "Multivariate analysis in relation to relapse-free survival revealed that T factor, lymph node metastasis, and KPNA2 expression (RR = 3.29; 95% CI = 1.77–6.75; P < 0.0001) were independent predictors of recurrence." (PMID 28178675, 2017). "KPNA2 protein expression in colon tissue microarray of tumor and normal tissue specimens and lymph node metastasis specimens obtained from 195 colon cancer patients were analyzed immunohistochemically." (PMID 26626145, 2015). "Immunolocalization of KPNA2 protein in the 195 primary colon tumors, as well as paired normal colon mucosa and 66 lymph node metastasis specimens in TMA." (PMID 26626145, 2015). "Furthermore, we performed a Chi-fang analysis, which revealed that KPNA2 mRNA levels were correlated with lymph node metastasis (p = 0.001) and the Lauren classification (p = 0.000) but not with age, sex, tumor site, or pathological stage of patients with GC (p > 0.05)." (PMID 39060340, 2024).
viral infection (6 papers, 2016 to 2025). "KPNA2 is implicated in a multitude of cellular processes, including differentiation, transcriptional regulation, immune response, viral infection, cellular maintenance and carcinogenesis." (PMID 27078844, 2016). "KPNA2 was involved in several cellular biological processes, including cell differentiation, development, viral infection, immune response, and transcriptional regulation." (PMID 36199790, 2022). "After viral infection, KPNA2 associates with IRF3 for nuclear import, and USP22 promotes this critical step by stabilizing KPNA2." (PMID 32645843, 2020). "When analyzing gene expression in A549 cells, results showed a decrease in KPNA2 (p = 0.0285) and an increase in KPNA5 (p = 0.0266) upon viral infection." (PMID 34696514, 2021). "USP22 controls nuclear accumulation of IRF3 and type I IFN signaling through KPNA2 deubiquitination only upon infection with SeV and HSV-1 and loss of USP22 expression decreased type I IFN responses upon virus infection, while USP22 deletion in uninfected cells did not trigger basal IFN signaling." (PMID 35933402, 2022).
esophageal cancer (4 papers, 2015 to 2021). A primary or metastatic malignant neoplasm involving the esophagus. "As reviewed previously, KPNA2 has been proposed to act as a diagnostic, prognostic, or predictive marker for various malignancies, including lung, gastric, bladder, breast, brain, prostate, ovarian, and esophageal cancers." (PMID 33728352, 2021).
gallbladder cancer (4 papers, 2020 to 2025). "Recent studies have revealed the oncogenic role of IPO3/KPNA4 in the head and oncogenic neck squamous cell carcinomas and the potential target of KPNA2 in gallbladder cancer." (PMID 32661323, 2020). "Findings obtained from a previous study suggest that E2F1 and E2F7 have different regulatory effects on KPNA2 to promote the development of gallbladder cancer." (PMID 33489876, 2020). "Additionally, KPNA2 promotes gallbladder cancer progression by regulating the nuclear localization of E2F1 and E2F7." (PMID 40830912, 2025). "Moreover, KPNA2 promotes tumor development through the nuclear localization of E2F1 and E2F7 in gallbladder cancer." (PMID 34903711, 2021).
Infertility (4 papers, 2023 to 2025). "We detected two heterozygous KPNA2 LoF variants in our cohort of infertile men, with this gene also having a predicted autosomal-dominant inheritance." (PMID 39388236, 2024). "However, we have not demonstrated the pathogenic role of mutant KPNA2 in our infertile cohorts." (PMID 36647821, 2023). "Previous studies have shown that male mice lacking KPNA2 exhibit reduced body size and sperm motility, increased sperm abnormalities, and disrupted testicular gene expression, ultimately leading to infertility." (PMID 41007398, 2025). "In summary, by experimentally disrupting the male germ cell orthoBackbone across evolutionarily distant species, we were able to uncover two new candidate genes for human infertility (HSPA2 and KPNA2) in addition to RNF113B, affecting a combined total of five individuals." (PMID 39388236, 2024). "Thus, we conclude that the function of KPNA2 in round spermatids is dispensable, as our mice do not show any signs of infertility." (PMID 39423201, 2024).
osteosarcoma (4 papers, 2020 to 2024). A usually aggressive malignant bone-forming mesenchymal neoplasm, predominantly affecting adolescents and young adults. "The purpose of the current study was to evaluate the KPNA2 expression level and its utility as a novel diagnostic biomarker in osteosarcomas and malignant bone tumor mimics, such as chondrosarcomas and Ewing sarcomas (ESs)." (PMID 33176814, 2020). "Our data demonstrate that KPNA2 is sufficiently reliable for use as a diagnostic marker in osteosarcoma biopsy samples." (PMID 33176814, 2020). "The purpose of the present study was to evaluate the expression of KPNA2 in osteosarcoma, chondrosarcoma and ES samples using immunohistochemistry to confirm its potential diagnostic utility as a novel molecular marker for discriminating osteosarcoma from other primary bone sarcomas." (PMID 33176814, 2020). "Although KPNA2 has been shown to be frequently expressed in OS as a new marker for the diagnosis, as well as in chondrosarcoma and Ewing sarcomas, the functions of KPNA2 in osteosarcoma are unclear." (PMID 36199790, 2022). "Several subtypes of osteosarcoma were analyzed, and immunostaining of KPNA2 was frequent in osteoblastic samples (90.9%), with 39 samples (70.9%) showing strong-intensity staining." (PMID 33176814, 2020). "Overall, both the extent and intensity of KPNA2 immunoexpression were highest in osteoblastic osteosarcomas among the types of bone tumors analyzed." (PMID 33176814, 2020). "Three of 4 (75%) telangiectatic and two of 3 (66.7%) giant cell-rich osteosarcoma samples had positive KPNA2 staining, with 50 and 33.3% of samples showing strong-intensity staining, respectively." (PMID 33176814, 2020). "We did note that the proportion of cells with positive KPNA2 expression was higher and the intensity of KPNA2 immunostaining was stronger in osteosarcoma samples than in samples of other high-grade bone sarcomas." (PMID 33176814, 2020). "Positive KPNA2 expression was observed in two of 6 (33.3%) fibroblastic osteosarcomas, with 2 (33.3%) samples showing strong-intensity staining." (PMID 33176814, 2020). "The data for 81 osteosarcoma (46 males and 35 females), 42 chondrosarcoma (21 males and 21 females) and 15 ES (11 males and 4 females) patients with both clinical and KPNA2 expression data were retrieved from hospital data files in 2020." (PMID 33176814, 2020). "KPNA2 was expressed in a lower proportion of chondrosarcoma and ES (6.7%) samples than osteosarcoma samples, and weak as well as diffuse staining was detected only in tumors." (PMID 33176814, 2020). "KPNA2 is frequently expressed in osteosarcomas, particularly in osteoblastic and chondroblastic tumors, but is rarely positive in chondrosarcomas and ESs." (PMID 33176814, 2020). "Our research reveals that KPNA2 expression is a sensitive and specific marker for osteosarcoma compared with chondrosarcoma and ES." (PMID 33176814, 2020). "In our study, we analyzed KPNA2 expression in osteosarcoma versus chondrosarcoma and ES samples and observed KPNA2 immunoreactivity in 81 osteosarcoma, 42 chondrosarcoma and 15 ES sections." (PMID 33176814, 2020). "We discovered that KPNA2 expression was significantly higher in osteosarcoma patient samples than in samples of other bone tumors." (PMID 33176814, 2020). "The results of the present study show that the expression of KPNA2 was significantly higher in osteosarcoma than benign bone tumor tissues." (PMID 33176814, 2020). "When KPNA2 expression was evaluated separately in the various subtypes of conventional osteosarcoma samples, osteoblastic and chondroblastic samples showed the greatest extent of staining, whereas more limited staining was observed in the fibroblastic samples." (PMID 33176814, 2020). "The expression of KPNA2 in osteosarcoma samples was much higher than that in chondrosarcoma and ES samples (P < 0.001)." (PMID 33176814, 2020).